CST3 (cystatin C)
Diseases named in the same sentence as CST3 in open-access papers (continued):
Sharing a sentence is not in itself a finding about the gene and the disease.
diabetes (continued). "Obese participants were more likely to be younger, female, shorter, with lower levels of serum creatinine, with higher levels of serum cystatin C, with systolic blood pressure (SBP), and with higher prevalence of diabetes and hypertension." (PMID 24868463, 2014). "Independent predictors of incident CAD, determined by logistic regression, were as follows: cystatin C, hs‐CRP, eGFR, HDLc after adjustments for age, creatinine, eGFR, homocysteine, gender, presence of hypertension, and diabetes." (PMID 24478035, 2014). "After combining all significant factors in a third model, gender, heart rate, diabetes, heart failure, urinary NGAL, cystatin C, BNP, and HbA1c remained significantly and independently correlated with ACR." (PMID 23844110, 2013). "BMI, SBP, cholesterol, triglycerides, CRP, cystatin c, serum GGT and diabetes prevalence increased with the age while HDL and serum albumin were opposite." (PMID 23947772, 2013). "Cystatin C has been shown to be an excellent marker of glomerular filtration rate (GFR) in healthy individuals and various disease states, including diabetes." (PMID 22350134, 2013). "In this study of a HF population, we found that cystatin-C levels were influenced by age, sex, NYHA functional class, eGFR, treatments, and comorbidities, such as diabetes and hypertension." (PMID 23240006, 2012). "Depending on the history of CVD the most important predictors for people with diabetes but without a history of CVD included: cystatin C, self-reported health satisfaction, biochemical measures of ill health (e.g. plasma albumin)." (PMID 40082712, 2025). "Cystatin C, as an indicator of kidney function, is commonly used to predict mortality in populations such as elderly males, patients with CVD, and individuals with diabetes." (PMID 40162314, 2025). "Compared to the midrange group, individuals in the negative eGFRdiff group had a significantly higher odds of diabetes, even after adjusting for the creatinine-based eGFR (OR: 1.21, 95% CI: 1.08–1.36) and cystatin C-based eGFR (OR: 1.32, 95% CI: 1.16–1.50)." (PMID 41280371, 2025). "Body fat or diabetes type did not significantly influence the accuracy of the cystatin C-based formulas." (PMID 39792299, 2025). "The results showed that 17 variables, including BMI, DBP, neutrophil count, albumin, serum creatinine, eGFR, serum cystatin C, triglycerides, serum IgG, serum C3, UPE, hematuria, CKD stage, nephrotic syndrome, diabetes, T, and C, were statistically significant factors (P < 0.05)." (PMID 39494280, 2024). "Three models were used: Model I (not adjusted for any covariates), Model II (adjusted for sex and age), Model III (adjusted for age, CRP, eGFR, sex; HDL-c, LDL-c, UA, CLD, PLT, Cystatin C; hypertension, HBA1C, diabetes; CKD, smoking, and drinking status variables)." (PMID 38402161, 2024). "The subgroup analysis showed that the effects of cystatin C were not strongly modified by age, BMI, smoking, hypertension, or diabetes status." (PMID 38681764, 2024). "Each unit of RC was associated with an 8.7% increase in stroke risk after adjusting for BMI, gender, age, drinking status, physical activity, heart diseases, diabetes mellitus, hypertension, lipid therapy, smoking status, CRP, Scr, and Cystatin C in Model 3 (HR = 1.087, 95%CI: 1.001–1.180)." (PMID 37880769, 2023). "There were statistically significant differences between the four groups regarding sex, age, BMI, smoking status, diabetes, CKD, ischemic stroke history, dyslipidemia and statin use, and HDL-C, UA, P, TG, FFA, Cr, cystatin C, HbA1C, TNT, and apoA levels (P < 0.05)." (PMID 37328790, 2023). "In the subgroup analysis, we found that the trend of the association between a low cystatin C level and RKFD was more significant in the younger subjects and in the subjects without diabetes, hypertension, metabolic syndrome, and gout." (PMID 36359307, 2022).
diabetes (continued). "Our findings discovered that cystatin C was a risk factor for diabetic nephropathy independent of BMI and SBP in diabetes mellitus patients." (PMID 36482996, 2022). "Several studies have been made to identify additional non-GFR determinants that affects creatinine and cystatin C levels, e.g., inflammation, diabetes, cancer and smoking." (PMID 35743877, 2022). "As muscle mass is frequently reduced in older adults, while plasma cystatin C is less affected, we explored the performance of CKD-EPI equations based on cystatin C alone and in combination with creatinine in older individuals with and without diabetes." (PMID 36033773, 2022). "PhenoAgeAccel PRS was more strongly associated than BioAgeAccel PRS with liver and kidney diseases and the associated biomarkers, for example, albumin, total bilirubin, creatinine, and cystatin C, plus COPD, hypothyroidism, type I and type II diabetes, and rheumatoid arthritis." (PMID 34038024, 2021). "Serum cystatin C levels were significantly higher in patients with diabetes mellitus than in their non-diabetic counterparts." (PMID 33401560, 2021). "We investigated if the concentration and “rangeability” of cystatin C (CysC) influenced the prognosis of coronavirus disease 2019 (COVID-19) in patients suffering from, or not suffering from, type 2 diabetes mellitus (T2DM)." (PMID 34234738, 2021). "Inverse univariate associations were found for age, BMI, smoking, cotinine excretion, SBP, DBP, coffee consumption, hs-CRP, GlycA, diabetes, glucose, total cholesterol:HDL cholesterol ratio, cystatin C, albumin excretion, and use of antihypertensives, antidiabetics, and statins (all P < 0.05)." (PMID 32899820, 2020). "Although some studies have found an association between cystatin C and BMI, percent body fat, and diabetes, the CKD-EPI cystatin C equation (CKD-EPICys) has been shown to have advantages over creatinine-based eGFR equations in patients in whom muscle mass is abnormally high." (PMID 32097414, 2020). "Our results indicate that diabetes patients had higher serum cystatin C levels than nondiabetic patients." (PMID 32306911, 2020). "Among the patients with CAD, those with diabetes mellitus had significantly higher serum cystatin C levels than those without diabetes mellitus (0.75 ± 0.10 vs 0.89 ± 0.11 mg/L, P<0.001)." (PMID 32306911, 2020). "Plasma levels of cystatin C were increased by 33% in males and females at week 8 of diabetes compared to nondiabetic mice, demonstrating mild renal function impairment in both sexes." (PMID 31535473, 2019). "No increase upon diabetes was observed in the vorapaxar treated mice, showing that vorapaxar limits the diabetes-induced increase in plasma cystatin C." (PMID 29774092, 2018). "In those with and without diabetes, cystatin C predicts CVD mortality and ESRD better than eGFR does." (PMID 29520581, 2018). "Several studies have reported that, like all endogenous markers of GFR, serum cystatin C concentration is independently associated with several non-GFR determinants including age, sex, diabetes, markers of obesity, inflammation, and smoking." (PMID 29016597, 2017). "Both urinary NAG and ACR were positively correlated with age, duration of diabetes, HbA1c, urinary GCR, and serum cystatin C. In contrast to urinary ACR, urinary NAG showed significant correlations with BMI, basal glucose, stimulated glucose, GA, PCGR, and HOMA-β." (PMID 27399115, 2016). "In univariate analyses, increasing age, lack of qualifications, smoking, increasing BMI, diabetes, hypertension, total cholesterol, HDL cholesterol were all significantly positively associated with cystatin C eGFR<60ml/min/1.73m2." (PMID 25700182, 2015). "We previously postulated that cystatin C level might also be a biomarker for HNF1A-MODY, a monogenic form of diabetes, as concomitant kidney phenotypes were described in this form of disease." (PMID 26347889, 2015).
diabetes (continued). "The lowest mean eGFR was consistently obtained by the spline Log cystatin C—age, sex, and weight equation regardless of diabetes or hypertension status." (PMID 24868463, 2014). "Independent correlates were SBP, uric acid, diabetes, total cholesterol, alanine amino transferase (ALT), Cystatin C and serum albumin (negative association) for overt albuminuria; and SBP, CRP and serum albumin only for microalbuminuria." (PMID 23947772, 2013). "Induction of diabetes by STZ led to significantly lower plasma cystatin C compared with non-diabetic controls (p<0.01), indicating that kidneys were still hyperfiltrating." (PMID 22900035, 2012). "The previous reports have suggested that serum cystatin C concentration is a better indicator of GFR than serum creatinine concentration in patients with spine injury, liver cirrhosis, diabetes, mild to moderate impaired kidney function, and in elderly patients." (PMID 23008697, 2012). "In this study, in which the new HbA1c criteria were applied for the diagnosis of pre-diabetes and diabetes, we observed a progressive and graded relationship between NT-proBNP, troponin T, hs-CRP and cystatin C tertile levels and the severity of angiographic CHD in high-risk patients." (PMID 21857933, 2011). "However, it was not related to age, tumor location, tumor size, diabetes, hypertension, clinical symptoms, and serum cystatin C level." (PMID 37483501, 2023). "Evidence from meta-analyses confirmed an excellent diagnostic performance of the serum cystatin C in the diagnosis of DKD, but the advantage of using serum cystatin C over creatinine in the estimates of GFR in diabetes could not be confirmed." (PMID 37545693, 2023). "Thus, we concluded that cystatin C was a risk factor in the development of DN independent of BMI and SBP in diabetes mellitus patients." (PMID 36482996, 2022). "Log Cystatin-C values at visit 3 were higher for every group compared to visit 1, and trends were consistent for all visits: those without diabetes had the lowest Cystatin-C levels, followed by those with diabetes and those that died over the observation period." (PMID 36094936, 2022). "However, once more in the diabetes scenario, cystatin C-based equations do not seem to outperform creatinine equations." (PMID 30723243, 2019). "In conclusion, our findings show that cystatin C measured in plasma might serve as a predictor of future MetS but not diabetes." (PMID 27218257, 2016). "Moreover, reclassification from preserved kidney function defined based on creatinine level to reduced kidney function using cystatin C occurred more often among persons with diabetes than among those without." (PMID 26347889, 2015). "Therefore, cystatin C might be used in patients with diabetes mellitus without concern of anthropometric data." (PMID 39792299, 2025). "The association between a low cystatin C level and a higher risk of RKFD was more significant in the patients who were younger, male, and had cardiovascular syndrome (p < 0.001) as well as in those without hypertension, diabetes, metabolic syndrome, or gout (p < 0.001)." (PMID 36359307, 2022). "We note that some of the identified features, such as HbA1c and cystatin C, predict CVD irrespective of the diabetes status." (PMID 40082712, 2025). "No statistical differences were observed in hypertension, diabetes mellitus, LVEF, albumin, hyperlipidemia, transient ischemic attack (TIA), cystatin C (Cys-C), D-Dimer, and history of drinking and smoking between two groups (P > 0.05, respectively)." (PMID 36386353, 2022). "While this meta-analysis reported sex and background differences in Cystatin-C; our study suggests that these are likely baseline differences that might be explained by accounting for mortality, and do not modify the relationship between Cystatin-C and diabetes." (PMID 36094936, 2022).
diabetes (continued). "In order to eliminate the influence of publication bias on meta-analysis, the trim and fill analysis were carried out in subgroup of cystatin C in severe OSAS and cystatin C in OSAS without diabetes." (PMID 32440991, 2021). "Except for the subgroup of cystatin C in severe OSAS and cystatin C in OSAS without diabetes, there was no significant publication bias in other subgroup." (PMID 32440991, 2021). "Most of these predictors (except for serum concentrations of cystatin C, NGAL, and uromodulin) were independent of age, diabetes duration, the presence of hypertension, heart failure, and the treatment with renin-angiotensin-aldosterone system inhibitors." (PMID 30158836, 2018). "In the UK replication study, we did not observe a difference in cystatin C levels between the UK HNF1A-MODY and other diabetes types, except HNF1B-MODY." (PMID 22350134, 2013). "For people with T2DM at the time of enrolment (w T2DM), Cystatin C was particularly important to predict all 6 CVD outcomes, with a feature importance of 0.028 for CHD in the “w T2DM” group, compared to only 0.001 in people without diabetes." (PMID 40082712, 2025). "Instead the following features were import to predict CVD in people with diabetes but without a history of CVD (“w T2DM”): HbA1c, cystatin C, self-reported health satisfaction, biochemical measures of ill health e.g. plasma albumin (representing liver and kidney damage)." (PMID 40082712, 2025). "Cystatin C may be influenced by different disease status; even in CKD with diabetes cohort, the nondiabetic kidney disease may confound results." (PMID 31636737, 2019). "While our nephrology department has been using Cystatin C in addition to sCr, it has not been implemented in our ICU due to its limitations in critically ill patients, such as being influenced by age, gender, race, diabetes, steroid treatments, thyroid dysfunction, and inflammation." (PMID 40141244, 2025). "The results of subgroup analysis showed that the serum cystatin C increased significantly in mild, moderate and severe OSAS The level of cystatin C was positively correlated with the severity of OSAS, whether they have hypertension and diabetes or not." (PMID 32440991, 2021). "Additionally, whilst cystatin C is not dependent on muscle mass, it has been reported to have other non-GFR determinants including sex, inflammation, obesity, diabetes, smoking, and thyroid dysfunction that may adversely affect GFR estimation in some populations." (PMID 29016597, 2017).
acute kidney injury (184 papers, 2006 to 2026). Sudden and sustained deterioration of the kidney function characterized by decreased glomerular filtration rate, increased serum creatinine or oliguria. "This review summarizes evidence from studies evaluating serum and urine cystatin C in healthy neonates and high-risk groups, including preterm newborns, neonates with acute kidney injury, and those with congenital kidney and urinary tract defects." (PMID 42072742, 2026). "The search terms included combinations of extracorporeal shock wave lithotripsy, shock wave lithotripsy, ESWL, urinary biomarker, neutrophil gelatinase-associated lipocalin, KIM-1, cystatin C, acute kidney injury, renal injury or renal function." (PMID 40978830, 2025). "This study aims to review relevant research and assess the diagnostic value of serum cystatin C (CysC) for post-cardiac surgery acute kidney injury (PCSAKI)." (PMID 39565808, 2024). "Cystatin-C and neutrophil gelatinase-associated lipocalin were found to be useful markers of hypoxic-acute kidney injury in premature calves with respiratory distress syndrome." (PMID 36670772, 2023). "After excluding acute kidney injury patients, ratio < 0.6 remained associated with higher cystatin C and urea levels." (PMID 37704948, 2023). "Previous investigations have demonstrated that cystatin C has good diagnostic accuracy for acute kidney injury in patients undergoing cardiac surgery and that it is a good predictor of the risk of death and cardiovascular events in elderly persons." (PMID 36359307, 2022). "Cystatin C (Cys C) used clinically for detecting early acute kidney injury (AKI) was reported to be associated with thyroid function." (PMID 30727972, 2019). "Urinary kidney injury molecule-1 (KIM-1), neutrophil gelatinase-associated lipocalin (NGAL), and serum cystatin C (Cys C) are biomarkers of acute kidney injury (AKI)." (PMID 29784944, 2018). "Five subjects had a low urine output, < 0.5 mL/h, indicating transient acute kidney injury, four of these had high plasma neutrophil gelatinase associated lipocalin and one high plasma cystatin C." (PMID 30255343, 2018). "Villa and colleagues compared the reciprocals of plasma cystatin C and creatinine with 24 h-CLCR in 50 critically ill patients at risk for developing acute renal failure, and reported a much stronger correlation for 1/cystatin C than for 1/creatinine." (PMID 25927897, 2015). "Explanation for this combination of results is based on the possibility that serum cystatin C have been the really marker involved in the pathogenesis of acute kidney injury and, therefore, high values were associated with increased mortality." (PMID 24967238, 2013). "Renal failure was associated with elevated serum resistin, as resistin correlated with creatinine (r = 0.462, P < 0.001) and cystatin C (r = 0.442, P < 0.001)." (PMID 19545363, 2009). "Cystatin C-estimated kidney function suggests that the observed association between vancomycin + piperacillin/tazobactam and creatinine-defined acute kidney injury may be pseudotoxicity." (PMID 37109649, 2023). "U-Gc combined with other glomerular and tubular injury markers (se-creatinine, u-orosomucoid, u-Cystatin-C, u-actin) might provide reliable clinical information regarding sepsis-associated acute kidney injury." (PMID 37836706, 2023). "Serum Cystatin C concentrations in particular were linked to COVID-19 mortality, severity, and the onset of acute kidney injury." (PMID 36361485, 2022). "A Chinese emergency cohort study showed that serum cystatin C, kidney injury molecule-1, neutrophil gelatinase-associated lipocalin, klotho, and fibroblast growth factor 23 are valuable in the early prediction of sepsis-related acute kidney injury." (PMID 36060071, 2022). "In one study, the serum cystatin C level strongly predicted all-cause acute kidney injury (AKI)." (PMID 32752030, 2020).